BPIFB1 (BPI fold containing family B member 1)
Diseases named in the same sentence as BPIFB1 in open-access papers:
BPIFB1 is named in the same sentence as 42 diseases in open-access papers, as found by Europe PMC text mining. Sharing a sentence is not in itself a finding about the gene and the disease. The quoted sentences say what the papers report.
nasopharyngeal carcinoma (13 papers, 2013 to 2025). A carcinoma arising from the nasopharyngeal epithelium. "It is decreased in nasopharyngeal carcinoma, gastic cancer, and lung cancer, which agrees with our findings that mucinous adenocarcinoma mucus has low expression of BPIFB1." (PMID 37005656, 2023). "Notably, decreased expression of BPIFA1 and BPIFB1 has been observed in nasopharyngeal carcinoma (NPC) biopsy samples." (PMID 41369347, 2025). "Moreover, a study showed that secreted protein BPIFB1 can inhibit LPS stimulated nasopharyngeal epithelium cell proliferation, and prevent carcinogenesis of nasopharyngeal carcinoma." (PMID 39095779, 2024). "Bactericidal/permeability-increasing fold-containing family B member 1 (BPIFB1) is hyperexpressed in nasopharyngeal epithelial cells and is markedly downregulated in nasopharyngeal carcinoma tissues; its expression is related to the prognosis of patients with nasopharyngeal carcinoma." (PMID 37394582, 2023). "Bactericidal/permeability-increasing-fold-containing family B member 1 (BPIFB1, previously named LPLUNC1) is highly expressed in the nasopharynx and significantly downregulated in nasopharyngeal carcinoma (NPC)." (PMID 29568064, 2018). "The overexpression of BPIFB1 markedly suppressed the expression of PD-L1, which in turn inhibited apoptosis and resulted in an increase in the expression of CD8 T cells in nasopharyngeal carcinoma cells." (PMID 40399547, 2025).
lung disease (6 papers, 2012 to 2024). "We previously identified polymorphisms in the BPIFA1/BPIFB1 region associated with CF lung disease severity." (PMID 31931521, 2020). "We previously demonstrated that genetic variants in the BPIFA1/BPIFB1 region are associated with decreased gene expression and increased lung disease severity in cystic fibrosis." (PMID 31931521, 2020). "In this study, we build upon our previous work by using an independent CF cohort to replicate the observation that genetic variation in the BPIFA1/BPIFB1 region is associated with CF lung disease severity." (PMID 31931521, 2020). "BPIFA1 and BPIFB1 have immunomodulatory activity and genetic variation associated with low levels of these proteins may increase CF lung disease severity." (PMID 31931521, 2020). "We evaluated whether the BPIFA1/BPIFB1 associations with lung disease severity replicated in individuals with CF participating in the International CF Gene Modifier Consortium (n = 6,365)." (PMID 31931521, 2020). "Moreover, we provide insight into the causal variant and gene responsible for this robust and replicated association, and we establish that BPIFA1 and BPIFB1 have immunomodulatory functions that may modify lung disease in CF." (PMID 31931521, 2020). "Beyond performing a chest CT, measurement of autoantibodies against BPIFB1 and KCNRG is a valuable diagnostic tool and should be considered as a screening modality in patients with thymoma and radiographic evidence of lung disease and/or chronic respiratory symptoms." (PMID 38954150, 2024). "In other lung disorders, BPIFB1 is increased in cystic fibrosis, COPD, asthma, and IPF." (PMID 37005656, 2023). "Furthermore, we investigated mechanisms by which the BPIFA1 and BPIFB1 proteins may modify lung disease in CF." (PMID 31931521, 2020). "Furthermore, our data support a new paradigm by which BPIFA1 and BPIFB1 may contribute to CF lung disease severity, resulting in gene expression changes in CF airway epithelial cells that could influence cell migration through Rho GTPase pathways and also by altering the response to viral infection." (PMID 31931521, 2020). "Building on our previous studies of BPIFA1 and BPIFB1 in normal lung and of BPIFA1 in CF tissue, the present study investigates the expression of BPIFB1 and BPIFA1 in lungs from CF patients and in bENaC-Tg mice with CF-like lung disease." (PMID 22767025, 2012). "Amongst top down-regulated isoforms, BPIFB1 (8-fold) and BPIFA1 (6-fold) are members of a family of secreted proteins with unclear biological role and function, but it has been reported that these proteins are differentially expressed in lung diseases." (PMID 28330331, 2016). "BPIFB1 levels were not different between genotypes, suggesting that decreased BPIFA1 may be responsible for the association between rs1078761 genotype and CF lung disease severity." (PMID 31931521, 2020).
cystic fibrosis (4 papers, 2020 to 2023). Autosomal recessive disorder caused by pathogenic variants in the CFTR gene (cystic fibrosis transmembrane conductance regulator), which encodes a chloride and bicarbonate channel expressed in epithelial cells, and follow the diagnosis criteria. "Bpifa1 and Bpifb1 are increased in cystic fibrosis and IPF, which is the most significantly increased secretome-associated protein in UIP." (PMID 37999562, 2023). "The BPIFB1 protein was reported to be upregulated in the small airway epithelium in cystic fibrosis compared to that in the control." (PMID 35714115, 2022). "Protein levels of both BPIFA1 and BPIFB1 have been shown to be upregulated in subjects with cystic fibrosis, suggesting that these molecules may have a role in the disease." (PMID 31931521, 2020).
lung carcinoma (3 papers, 2022 to 2025). "Given that, it was found that mutations occurring in BPIFB1 promote the risk of lung cancer, and its downregulation leads to poor prognosis in lung cancer patients." (PMID 36613598, 2022). "In our study, the expression of CLIC6, CLDN2, and BPIFB1 was significantly upregulated in H1975 and A549 cells, suggesting that high expression of these genes may influence the progression of lung cancer through immune regulation." (PMID 40399547, 2025). "Overall, these data imply that the differentially expressed FCGBP, F5, CFB, and BPIFB1 in lung cancer may play an important role in lung cancer progression." (PMID 36613598, 2022). "FCGBP, BPIFB1, F5, CFB, and CST1 and their correlation to EMT key markers displayed a potentially less metastatic phenotype of lung cancer under SMG." (PMID 36613598, 2022).
Obesity (3 papers, 2022 to 2024). Accumulation of substantial excess body fat. "Three protein markers: IGFBP1, BPIFB1 and COL4A1 were significantly underexpressed, comparing between participants with obesity and NOH group." (PMID 38548792, 2024). "Three proteins underexpressed with obesity (IGFBP1, BPIFB1 and COL4A1) were clustered in the turquoise cluster and overlapped with ER lumen and collagen-containing extracellular matrix GO terms." (PMID 38548792, 2024). "We only found five genes shared between both groups (MUCL3, PGC, TCN1, TFF2, BPIFB1) that were upregulated in MO-low-IR but downregulated in MO-high-IR when compared with women without obesity." (PMID 35625760, 2022).
autoimmune conditions (2 papers, 2017 to 2024). "Together these results with interferon-γ and BPIFB-1, highlight the high performance of LIPSTICKS for the ultrarapid detection of autoantibodies directed against extracellular targets associated with autoimmune conditions." (PMID 28630417, 2017). "Of note, most of these patients were negative for other autoantibodies associated with autoimmunity and/or lung autoimmunity in other conditions (KCNRG, BPIFB1, TRIM38, CENP-A, interferon-ω, ABLIM, and CDHR) suggesting some specificity for ILD in the context of SjD." (PMID 39524452, 2024).
cholera (2 papers, 2013 to 2020). "Evidence that BPIFB1 plays a role in innate immunity comes from a genetic association with clinical outcomes in cholera in combination with data indicating that BPIFB1 modifies the innate immune response to Vibrio cholera." (PMID 31931521, 2020).
interstitial lung disease (2 papers, 2017 to 2019). A diverse group of lung diseases that affect the lung parenchyma. "Two downregulated genes (BPIFB1 and CAMP) in this group had been reported to be involved in interstitial lung disease, psoriasis, rosacea, or other skin inflammatory disorders." (PMID 31068931, 2019).
papillary cystadenocarcinoma (2 papers, 2017 to 2019). A malignant cystic serous or mucinous epithelial neoplasm characterized by the presence of malignant glandular epithelial cells forming papillary structures. "Bpifb1 has been found to be overexpressed in mucous cells of salivary gland tumors of papillary cystadenocarcinoma." (PMID 28201999, 2017).
pneumonitis (2 papers, 2020 to 2024). An inflammatory process affecting the lung parenchyma. "In addition, some thymoma patients carry autoantibodies against the lung-targeted bactericidal/permeability-increasing fold-containing B1 (BPIFB1), the potassium channel regulator (KCNRG), or both, which are also seen in APECED-associated pneumonitis." (PMID 38954150, 2024). "Titers of BPIFB1 and KCNRG autoantibodies did not decline despite clinical and radiographic remission of pneumonitis, further suggesting that the pathogenic role of B-cells might be conferred via priming of T-cells in the lung tissue, rather than through autoantibody production." (PMID 33584685, 2020).
autoimmune disease (1 paper, 2021). A disorder resulting from loss of function or tissue destruction of an organ or multiple organs, arising from humoral or cellular immune responses of the individual to their own tissue constituents. "Thus, BPIFB1 may also affect the progression of autoimmune diseases." (PMID 34516718, 2021).
autoimmune polyendocrinopathy-candidiasis-ectodermal dystrophy (1 paper, 2024). "Autoantibody testing against two other autoantigens, KCNRG and BPIFB1, found in autoimmune polyendocrinopathy-candidiasis-ectodermal dystrophy (APECED) patients with autoimmune pneumonia, revealed no seropositivity in any of the SjD or IIM subjects (data not shown)." (PMID 39524452, 2024).
bacterial pneumonia (1 paper, 2012). Acute infection of the lung parenchyma caused by bacteria (e.g., Streptococcus pneumoniae, Haemophilus influenzae, Chlamydia pneumoniae, Mycoplasma pneumoniae, and Legionella pneumophila). "BPIFB1 was localized in CF lung samples along with BPIFA1, MUC5AC, CD68 and NE and directly compared to histologically normal lung tissues and that of bacterial pneumonia." (PMID 22767025, 2012). "We addressed these issues using cases of bacterial pneumonia where significant numbers of neutrophils and macrophages were seen but where no BPIFB1 staining was noted." (PMID 22767025, 2012). "Macrophages and neutrophils in lungs from bacterial pneumonia also did not express BPIFB1." (PMID 22767025, 2012).
breast carcinoma (1 paper, 2025). "BPIFB1 has been shown to promote the spread of breast cancer that tests positive for hormone receptors, the process that involves driving macrophage M2-like polarization." (PMID 40399547, 2025).
bronchiectasis (1 paper, 2021). Segmental, irreversible dilation of the bronchial tree resulting in the accumulation of secretions which leads to obstruction. "A bronchoscopy should be performed in patients with radiographic evidence of bronchiectasis and/or ground glass or nodular opacities and/or in patients with abnormal pulmonary function testing, even when BPIFB1 and/or KCNRG autoantibodies are negative." (PMID 34790633, 2021).
cervical cancer (1 paper, 2024). A primary or metastatic malignant neoplasm involving the cervix. "We speculated that BPIFB1 may involve in the pathogenesis of cervical cancer." (PMID 39095779, 2024).
Crohn disease (1 paper, 2024). A gastrointestinal disorder characterized by chronic inflammation involving all layers of the intestinal wall, noncaseating granulomas affecting the intestinal wall and regional lymph nodes, and transmural fibrosis. "A scRNA-seq study of paediatric treatment-naive patients with Crohn’s disease identified MUC6+TFF2+ and BPIFB1+AQP5+ populations, albeit annotated as goblet cells." (PMID 39567783, 2024). "We located INFLAREs (MUC6+AQP5+BPIFB1+) at the crypt base and surface foveolar cells (MUC5AC+) at the crypt top of metaplastic glands in Crohn’s disease mucosa." (PMID 39567783, 2024).
dental caries (1 paper, 2018). The decay of a tooth, in which it becomes softened, discolored, and/or porous. "On the other hand, 3 non-age-specific proteins, including histatin-1, BPI fold-containing family B member 1, and alpha-enolase were determined to be associated with dental caries." (PMID 30359274, 2018). "Moreover, non-age-specific proteins (histatin-1 and BPI fold-containing family B member 1) were verified to be important candidate biomarkers for common dental caries." (PMID 30359274, 2018). "Moreover, two differentially expressed proteins, histatin-1 and BPI fold-containing family B member 1, were validated to be non-age-specific candidate biomarkers of dental caries, which may advance our utilization of salivary diagnostics for caries risk assessment." (PMID 30359274, 2018).
endometriosis (1 paper, 2020). The growth of functional endometrial tissue in anatomic sites outside the uterine body. "Repeated genes associated with P-phase (ACTB, ANXA4, BPIFB1, EPHX1, MUC5B, PRDX2, and VIM) could indicate stronger genetic causes associated with pathophysiology of endometriosis." (PMID 32474803, 2020).
infertile (1 paper, 2022). "The expression of LCP1, CTSH, BPIFB1 and Quiescin sulfhydryl oxidase 1 (QSOX1) is significantly higher in infertile receptive phase uterine lavage compared to fertile." (PMID 36589798, 2022).
mucinous adenocarcinoma (1 paper, 2023). An invasive adenocarcinoma composed of malignant glandular cells which contain intracytoplasmic mucin. "We find that (BPI) fold-containing family B member 1 (BPIFB1) is the most significantly increased secretome-associated protein in UIP, whereas Mucin-5AC (MUC5AC) is the most significantly increased in mucinous adenocarcinoma." (PMID 37005656, 2023). "To validate this result, we performed immunofluorescence on both mucinous adenocarcinoma (n = 3) and UIP specimens (n = 4) for MUC5B, MUC5AC, and BPIFB1." (PMID 37005656, 2023). "Thus, a distinguishing factor for fibrotic/UIP mucus is the high abundance of MUC5B and BPIFB1, whereas MUC5AC is predominant in mucinous adenocarcinoma mucus." (PMID 37005656, 2023). "Inversely, mucinous adenocarcinoma mucus was positive for MUC5AC, whereas MUC5B and BPIFB1 are largely negative at the immunofluorescence level (white arrows point where MUC5B/BPIFB1 are absent)." (PMID 37005656, 2023).
pulmonary fibrosis (1 paper, 2025). Chronic progressive interstitial lung disorder characterized by the replacement of the lung tissue by connective tissue, leading to progressive dyspnea, respiratory failure, or right heart failure. "It has also been shown that COPD airways have elevated levels of BPIFB1 when compared to asymptomatic controls, and overexpression of BPIFB1 in macrophages is thought to promote pulmonary fibrosis and impair lung function." (PMID 41550953, 2025).
tumor (15 papers, 2013 to 2025). "BPIFB1 is a secretory protein that is implicated in immune regulatory functions and shown to have anti-tumor effects." (PMID 37005656, 2023). "BPIFB1 is a potential tumor suppressor that regulates NPC cell growth by downregulating the MAPK and cyclin D1/E2F pathways." (PMID 29568064, 2018). "PRMTs may promote tumor development by influencing immune escape through the CLIC6/CLDN2/BPIFB1 axis." (PMID 40399547, 2025). "Top upregulated genes linked to humoural immune response, such as BPIFB1 and IGHM may play an critical roles in tumour development." (PMID 40847563, 2025). "Most of the studies on KIR2DL4 and BPIFB1 are tumor-oriented, and the expression of KIR2DL4 and BPIFB1 in AMI samples is down-regulated, which may be helpful for AMI research." (PMID 39417451, 2024). "Moreover, it has been reported that BPIFB1 is abnormally expressed in tumours, which suggests that it plays a role in tumour development." (PMID 34877770, 2022). "In respiratory diseases, BPIFB1 is shown to exhibit anti-tumor and anti-metastatic effects; however, the exact mechanisms remain unclear, warranting further investigation." (PMID 36613598, 2022).
cancer (7 papers, 2013 to 2026). A tumor composed of atypical neoplastic, often pleomorphic cells that invade other tissues. "Variants in four genes (ROPN1, PRSS3, BPIFB1, and BCORL1) were detected in all individuals from Family 2, while four (TUBB2B, CAFAP54, PSG2, and SIRPB1) were exclusive of the MPT21 index case and her relative with cancer (MPT21.2)." (PMID 39408606, 2024). "We further validated the potential of the three identified genes, S100P, BPIFB1, and SLC6A14, as biomarkers for predicting the recurrence of early-stage cancer." (PMID 37152984, 2023).
infection (4 papers, 2018 to 2024). The state of being infected such as from the introduction of a foreign agent such as serum, vaccine, antigenic substance or organism. "Differential gene expression analysis revealed a common epithelial host response to mycobacteria, including upregulation of BIRC3, S100A8 and DEFB4, and downregulation of BPIFB1 at 48 h post infection." (PMID 37822359, 2023). "Finally, immune factors prevent pathogenic infection in vertebrate gestational tissues, and our dataset identifies several candidate genes responsible for immune defence in the pregnant dunnart uterus (BPI, BPIFB1, GZMA and PRF1)." (PMID 29402916, 2018).
bacterial infection (1 paper, 2025). "Amongst the proteins identified during proteomic analysis that were decreased in CepEVs were DEFA3, LYZ, CAMP, LTF, and BPIFB1, all of which had strong associations with defense response to bacterium (GO: 0042742), as well as the immune response to bacterial infection." (PMID 41550953, 2025).
BPIFB1 also shares sentences with these, for which no sentence is quoted: asthma (1 paper); chronic rhinosinusitis (1); Influenza Infection (1); mucoepidermoid carcinoma (1); nasal polyp (1); neurodegenerative disease (1); osteosarcoma (1); prostate carcinoma (1); psoriasis (1); respiratory diseases (1); rosacea (1); salivary gland tumors (1); skin inflammatory disorders (1); Telangiectasia (1); thymoma (1); viral infection (1).